IL1B (interleukin 1 beta)
Diseases named in the same sentence as IL1B in open-access papers (continued):
Sharing a sentence is not in itself a finding about the gene and the disease.
COVID-19 (continued). "Thus, more profound inhibition of IL-1β and/or concomitant inhibition of other pathogenic cytokines should be explored to combat severe COVID-19." (PMID 40016339, 2025). "Furthermore, several studies confirm that severe immune dysregulation during COVID-19 progression, along with inflammasome-associated cytokines such as IL-1β and IL-18, is significantly associated with vascular damage." (PMID 41357188, 2025). "Additionally, a subgroup of patients with COVID-19 was linked to increased levels of IL-1β, severe cytokine storm and hyperinflammatory symptoms." (PMID 40547021, 2025). "The heterozygous genotype of the rs16944 (IL1B) variant and the presence of the A allele showed a significant association with increased susceptibility to severe COVID-19 outcomes, including hospitalization and ICU admission, suggesting a possible contributory role in disease severity." (PMID 40506975, 2025). "Several studies reported an association between IL-1β and IL-18 serum levels and severe COVID-19." (PMID 40016339, 2025). "Canakinumab, a human monoclonal antibody targeting IL-1β, is associated with the reduction of serum C-reactive protein level and the improvement of overall mortality in COVID-19; case reports showed that canakinumab can reduce the risk of recurrence of systemic disease-related pericarditis." (PMID 38455049, 2024). "Both patients with active AOSD or with severe coronavirus disease-2019 showed elevated Gal-3 and cytokines, including IL-1β, IL-6, and IL-18, supporting a common link of cytokine storm in their pathogenesis." (PMID 38711500, 2024). "The IL-1β rs1143634 SNP T allele was protective against severe COVID-19, while the IL-6R rs12083537 G allele and the IL-1β rs16944 C allele were markedly related to COVID-19 severity among Egyptians." (PMID 39452786, 2024). "Additionally, the COVID-19 cases included in the present study had IL-1β rs16944 CC genotype associated with risk to COVID-19 severity and mortality." (PMID 39452786, 2024). "Insights into the link between the Interleukin-6 receptor (IL-6R) and Interleukin-1 beta (IL-1β) genetic variation and severe coronavirus disease 2019 (COVID-19) are crucial for developing new predictors and therapeutic targets." (PMID 39452786, 2024). "Moreover, the correlation and impact of miR-9 on the expression of pro-inflammatory cytokines IL-6, IL-1β, and TNFα, which are critical mediators in the inflammatory response associated with COVID-19 severity, were also assessed." (PMID 39201618, 2024). "In addition, the COVID-19 cases were significantly associated with IL-1β rs16944 CC genotype and the C allele." (PMID 39452786, 2024). "A dysregulation in cytokine content has been linked to T cell exhaustion in patients who recovered from COVID-19 (n = 39), with higher levels of IL-1β, IL-1RA, IL-7, IL-8, IL-10, IFN-γ, and MIP-1α, and a decrease in IL-9, CCL11, MIP-1β, and RANTES, as compared with healthy controls (n = 43)." (PMID 38549752, 2024). "In the periphery, it has been observed that monocytes from COVID-19 patients have increased inflammasome activation and undergo pyroptosis, which is associated with higher levels of plasma IL-1β in critically ill patients, and the presence of ASC speck formation in lung macrophages." (PMID 36316366, 2023). "High levels of cytokines, such as IL-2, IL-1b, and IL-10, may be associated with thrombotic complications in patients with COVID-19." (PMID 37112918, 2023). "Similarly, increased TNF-alpha and IL-1β levels are associated with a dysregulated immune response and organ damage in severe COVID-19 patients." (PMID 37629267, 2023). "Proinflammatory cytokines and acute-phase reactants such as IL-1β and IL-18 caused by COVID-19 around NLRP3 activation may directly or indirectly cause inflammation and pancreatic β cell damage, resulting in severe insulin resistance and hyperglycemia." (PMID 37868953, 2023).
COVID-19 (continued). "Interestingly, IL-6 and IL-1β have both been implicated in the dysregulation (altering the normal levels) of DMETs, and their presence in COVID-19 pathophysiology warrants a similar investigation." (PMID 37180730, 2023). "We also identified a pro-inflammatory cytokine profile associated with COVID-19, highlighting the IL-6 and IL-1β, which may work as potential biomarkers or predictors of long-COVID-19 when used alone or in combination with IFN-γ." (PMID 37018291, 2023). "However, the brain inflammation associated with COVID-19 increases the concentration of cytokines that negatively affect adult human neurogenesis, e.g., IL-6, IL-1β, IL-1α, and TNF." (PMID 36672177, 2023). "Here, we present evidence that periodontitis and GCF IL-1β are COVID-19 risk factors." (PMID 36718446, 2023). "ARDS is the leading cause of death due to COVID-19, characterized by high levels of pro-inflammatory cytokines (IL-6, IL-17, IL-1β, and TNF-α) and immune cell hyperactivation, a state called “cytokine storm” that may lead to multiorgan failure." (PMID 37368708, 2023). "This study aimed to evaluate the expression of NLR family pyrin domain containing 1 (NLRP1), NLRP3, and Apoptosis-associated speck-like protein containing a CARD (ASC) as well as their association with serum level of interleukin (IL)-1β in patients with coronavirus disease 2019 (COVID-19)." (PMID 37723427, 2023). "Our work suggests that targeting inflammasome-dependent IL-1β/IL-18 and/or purinergic signaling pathways may offer a novel opportunity for the treatment of viral infection and hyper-inflammation associated with COVID-19." (PMID 37920468, 2023). "We explored whether there is a causal association between the periodontitis-related phenotypes and COVID-19, and found that increased GCF IL-1β levels also increase COVID-19 susceptibility." (PMID 36718446, 2023). "Keeping aside the role of IL-1β protein as a potential therapeutic target for dry eye disease and COVID-19, its inhibitors have also been implicated to have a central role in the treatment of myeloma, rheumatoid arthritis, amyotrophic lateral sclerosis (ALS), etc.." (PMID 37446547, 2023). "In this regard, a study conducted in an ACE2 humanized mouse model of COVID-19 showed that, in response to infection, macrophages activate inflammasomes causing the release of IL-1β and IL-18 and undergo pyroptosis, thus favoring the pathogenesis of acute lung injury." (PMID 37662901, 2023). "Furthermore, this synergistic combination of acetate and ALA significantly increased the expression of host interferon-β (IFN-β) and decreased the expression of host interleukins IL-1β and IL-6, which are associated with severe COVID-19." (PMID 37515117, 2023). "Therefore, it would be intriguing to conduct in vitro experiments to assess the potential of the selected hit compounds for mitigating dysregulated expression of IL-1β, an underlying factor contributing to the severity of both COVID-19 and dry eye disease." (PMID 37446547, 2023). "We examined whether COVID-19-associated pEVs could modulate IL-1β/TNF-α/IL-8 expression in neutrophils." (PMID 37904132, 2023). "Furthermore, an elegant longitudinal study performed in patients with COVID-19 found a correlation between the late-stage pathology in COVID-19 and cytokines linked to the inflammasome pathway, including IL-1β and IL-18." (PMID 37113134, 2023). "Additionally, the pathogenesis of COVID-19 is associated with elevated cytokines such as IL-1β, IL-6, and TNF-α." (PMID 36160713, 2022). "Higher serum levels of IL-1β are associated with increased COVID-19 severity, and may allow the identification of patients at higher risk for poor clinical outcomes." (PMID 36209522, 2022). "In severe COVID-19 patients, the diagnostic performance was good for IL-6 (AUC = 0.844), fair (acceptable) for IL-18 (AUC = 0.785) and IL-35 (AUC = 0.742), and poor for IL-1β (AUC = 0.604)." (PMID 36675695, 2022).
COVID-19 (continued). "Also, the study observed a positive association between neutrophils and each of plasma IL-1β and IL-17 in the active COVID-19 cases." (PMID 36094915, 2022). "Sera biomarkers that indicate cardiac damage, inflammation and thrombosis such as troponin T and I, CRP, tumor necrosis factor (TNF), IL-1β and IL-6 have been found to be associated with increased mortality as well as being elevated in males with COVID-19 compared to females." (PMID 36292038, 2022). "Although there are no direct assessments that NETs contribute to the cytokine storm in the respiratory failure in patients with severe COVID-19, although evidence indicates that proinflammatory cytokines, such as IL-1β and IL-6, are closely linked to NET production during severe infection." (PMID 36439786, 2022). "Patients with more severe forms of COVID-19 might be at high risk, as it was demonstrated that elevated levels of IL-6 and high IL-1β levels are correlated with a poor prognosis in the setting of ACS." (PMID 35888173, 2022). "Furthermore, clinical reports have associated COVID-19 severity with elevated blood cytokine levels of TNFα and IL-1β." (PMID 36136963, 2022). "Upon SASR-CoV-2 infection, the pro-inflammatory activity of macrophages was enhanced, as indicated by the increased expression of inflammatory cytokines (IL-1β, IL-6) and chemokines (CXCL10) by macrophages." (PMID 36505489, 2022). "Strikingly, combined stimulation of anti-spike IgG immune complexes and the toll-like receptor 3 agonist, polyinosinic:polycytidylic acid (poly(I:C)) increased the production of COVID-19-associated pro-inflammatory cytokines IL-1β, IL-6, and TNF compared to IgG or poly(I:C) alone." (PMID 33979301, 2021). "Also, itaconate and its derivative 4-Octyl itaconate, (4-OI), inhibits NOD-, LRR-, and pyrin domain-containing protein 3 (NLRP3) inflammasome activation, preventing the secretion of IL-1β which is implicated in COVID-19 immunopathology." (PMID 34240083, 2021). "Finally, elevated serum levels of proinflammatory cytokines, such as IL-6 and IL-1β, in critically ill patients with COVID-19 were found to be associated with abnormal coagulation parameters, which are caused by endothelial dysfunction." (PMID 34253862, 2021). "This shows that the expression of IL-1α, IL-1β, and its signaling pathway molecules increase within 3-5 days post disease onset and might be positively associated with poor prognosis of COVID-19." (PMID 35126355, 2021). "We consecutively included patients during the first peak of the COVID-19 epidemic in Brazil and analyzed the expressions of genes encoding interleukin (IL)-1β, IL-6, IL-8, IL-10, IL-12A, IL-12B, and tumor necrosis factor-α in peripheral blood mononuclear cells." (PMID 33819170, 2021). "Previous studies also showed that Blautia and Ruminococcus were positively correlated with the expression of these two cytokines, and the pro-inflammatory status caused by the increase of IL-1β may cause the deterioration of patients with COVID-19." (PMID 34863291, 2021). "Direct correlations between COVID-19 outcomes and individual cytokines and immune cell populations indicate symptoms of COVID-19 are associated with elevations in interleukin 1 beta (IL-1β), IL-6, interleukin 10 (IL-10), and TNFα), as well as a general lymphopenia." (PMID 33967944, 2021). "COVID-19 studies highlight the significant increase in pro-inflammatory factors that can also be found in the brain; in particular, in animal models, caspase-1 activation causes higher cleaved caspase-3 levels with consequent activation of IL-1β." (PMID 32973818, 2020). "Interleukin 6 (IL-6), interferon gamma-induced protein 10 (IP-10), tumor necrosis factor (TNF) α and interleukin 1β (IL-1β) implicated as inflammatory factors associated with COVID-19 progression were detected in the alveoli with diffuse immune cell infiltration." (PMID 34676085, 2020).
COVID-19 (continued). "Further supporting these findings, we found that the gene most depressed in expression in COVID-19 patients compared to those with other viral ARIs was IL1B, which encodes a pro-inflammatory cytokine produced by the inflammasome complex, particularly in macrophages." (PMID 33203890, 2020). "Moreover, single cell analysis of PBMCs has reported the presence of a monocyte subset unique to severe COVID-19 patients that is enriched in genes encoding a range of cytokine storm related cytokines such as IL-1β, IL-6, and TNF-α." (PMID 33123152, 2020). "Similarly, IL-1β antagonists or NLRP3 inflammasome inhibitors may be tested in COVID-19-associated coagulopathy to evaluate their ability to reduce thrombo-inflammatory complications." (PMID 41311551, 2025). "Additionally, COVID-19 is linked to a proinflammatory shift in pregnant individuals, characterized by a reduction in Th2 cells and a lowered Treg/Th17 ratio, alongside an elevated Th1/Th2 ratio and IL-1β and IL-18 levels." (PMID 40497938, 2025). "In addition, recent reports on COVID-19 highlight that neutrophils could be a major source of inflammasome derived IL-1β, which has been implicated as a substantial contributor to COVID-19 pneumonia." (PMID 39172744, 2024). "In COVID-19 patients, the level of inflammatory cytokines is increased and plays a crucial role in the pathogenesis of the disease; among them, interferon-γ (IFNγ), TNFα, IL-1β and IL-6 are indicated as the key cytokines associated with the severity of COVID-19." (PMID 38542436, 2024). "Elevated IL-1β and IL-6 responses have been associated with disease severity, suggesting that IL-1β and/or IL-6 may be key drivers of pathology in severe COVID-19." (PMID 37283924, 2023). "However, exactly how IL-1β affects COVID-19 remains unclear, and the association between GCF IL-1β and SARS-CoV-2 infection warrants further exploration." (PMID 36718446, 2023). "In addition to high early IFN responses, moderate COVID-19 is associated with increased plasma levels of a core of pro-inflammatory cytokines, chemokines and growth factors (e.g., IL-1a, IL-1β, IFNα, IL-12p70, and IL-17A) that are effectively resolved during infection." (PMID 37491352, 2023). "Furthermore, we demonstrate for the first time that higher GCF IL-1β levels elevate COVID-19 risk, suggesting a novel mechanism through which SARS-CoV-2 might cause an individual onset of COVID-19 through the IL-1β-related pathways." (PMID 36718446, 2023). "The statistical analysis suggested that the predicted cytokine levels captured the hidden inflammatory parts of the cytokine levels with significant associations with COVID-19 mortality, while the original cytokine levels may also always accomplish, e.g., IL-1β." (PMID 37735372, 2023). "IL-1β and TNFα are also potent activators of neutrophils that are attracted by IL-8 and release large amount of neutrophil extracellular traps (NETs) that are present in the sera of COVID-19 patients and are correlated with both progressive loss of lung functionality and thrombosis." (PMID 35563218, 2022). "The NIC-hLYS particles exhibited suppression of the inflammatory cytokines TNF-α and IL-6, which have been implicated in the development of more severe COVID-19, while elevating the production of the inflammatory cytokine IL-1β, which may contribute to enhanced antiviral activity." (PMID 33571320, 2021). "It should be noted that proinflammatory cytokines such as TNF-α, IL6, and IL1β may promote the disruption of lipid metabolism resulting in systemic inflammation, and that COVID-19 itself has been associated with dyslipidemia, which may worsen obesity-associated dyslipidemia." (PMID 34281182, 2021). "Furthermore, SPM reduce the production of pro-inflammatory cytokines, including those involved in SARS-Cov-2 such as IL-6 and IL-1β." (PMID 34437568, 2021). "There was a significant correlation between IL-1β and time elapsed since COVID-19 vaccination (r = 0.58, p < 0.05)." (PMID 41601910, 2026).
COVID-19 (continued). "Acute COVID-19 features an imbalanced host response marked by elevations of IL-1β, IL-6, IL-8, TNF-α and interferon-inducible chemokines (e.g., CXCL9/CXCL10) that govern myeloid recruitment, T-cell positioning, angiogenesis, and tissue remodeling." (PMID 41440526, 2025). "In this context, the association between genetic variants in the IL1B, IL6, and TNF genes and the severity of COVID-19 was explored, with particular emphasis on outcomes such as hospitalization, the need for ICU admission, and mortality." (PMID 40506975, 2025). "Numerous studies have reported increased serum levels of IL-6 in COVID-19 patients, with its release significantly amplified by IL-1β and TNF-α during early inflammation." (PMID 40219044, 2025). "In contrast, we found that other markers often used to measure inflammaging, including IL-6, IL-1b, and TNF-a, showed weaker associations with naïve T cells or odds of hospitalization or death from COVID-19." (PMID 41280118, 2025). "By activating SARS-CoV-2 and other toll-like receptors, a variety of proinflammatory mediators, including IL-6 and IL-1β, are released, potentially contributing to the pathology of COVID-19." (PMID 41002604, 2025). "During acute COVID-19, CD25 levels were positively associated with several serum inflammation markers, including C-reactive protein (CRP), IL-1β, IL-6, IL-10, and tumor necrosis factor (TNF)." (PMID 41310351, 2025). "This is because IL-1α, IL-1β, IL-5, IL-8, NF-κβ, and interferons (α, β, and γ), are molecules that overlap with the immune response to COVID-19." (PMID 39941142, 2025). "The incidence of HT among COVID-19 patients has sparked renewed interest among researchers, as these patients produce an excess of inflammatory cytokines (IL-6, IL-1β, IFN-γ, TNF-α)." (PMID 40584613, 2025). "Individuals with either flu-like symptoms or infected with COVID-19 residing in EA exhibited higher production of IL-12p70, IL-6, IL-1β, IL-2, and IL-1ra compared to NEA residents." (PMID 40165959, 2025). "A study indicated that the inflammatory profile (CRP, IL-10, IL-17, IL-6, TNFα, and IL-1β) observed during the acute phase of severe COVID-19 predicts future long COVID symptoms." (PMID 40048451, 2025). "The elevated levels of IL-1β and IL-18 observed in COVID-19 patients with CRS support the involvement of the DDR and DNA sensing, via downstream inflammasome activation, amplifying inflammation and contributing to tissue injury." (PMID 40788382, 2025). "Other studies in COVID-19 patients admitted to hospital documented an early and transient elevation in IL-1β levels, and this cytokine is known to peak early during many infections." (PMID 39267408, 2025). "Concerning systemic immunity in COVID-19, clinical studies have shown a significant rise in pro-inflammatory cytokines and chemokines (IL-1β, IL-2, IL-6, IL-8, IL-15, IFN-γ, TNF, MCP-1), characterizing cytokine release syndrome (CRS) or cytokine storm." (PMID 40572294, 2025). "This study aims to address this gap by investigating the association between thirteen functional variants in IL1B, IL6, and TNF and severe COVID-19 outcomes in 500 unvaccinated individuals from southern Brazil." (PMID 40506975, 2025). "COVID-19 is characterized by a systemic inflammatory response with elevated cytokines, including IL-6, IL-1β, TNF-α, and interferon-γ." (PMID 41446486, 2025). "Initially, we observed a high concentration of IL-6 and IL-1β in COVID-19 patients compared with controls, indicating disease severity in these patients (Supplementary data_Table S1)." (PMID 40709999, 2025). "In COVID-19, immune effector cells secrete high levels of chemokines and proinflammatory cytokines (e.g., TGFβ, TNFα, IL-33, IL-18, IL-12, IFNγ, IL-6, IL-1β, and IFN-α) in response to SARS-CoV-2 infection." (PMID 40002929, 2025). "Studies have shown that circulating levels of IL-6, TNF-α, and IL-1β are significantly elevated in COVID-19 patients with severe disease." (PMID 40806851, 2025).